EARS2 (glutamyl-tRNA synthetase 2, mitochondrial)
Description:
Non-discriminating glutamyl-tRNA synthetase that catalyzes aminoacylation of both mitochondrial tRNA(Glu) and tRNA(Gln) and participates in RNA aminoacylation for mitochondrial protein translation. Attachs glutamate to tRNA(Glu) or tRNA(Gln) in a two-step reaction: glutamate is first activated by ATP to form Glu-AMP and then transferred to the acceptor end of tRNA(Glu) or tRNA(Gln). In vitro, cytoplasmic tRNA(Gln) is slightly glutamylated, but with low activity.
Synonyms: GluRS; mtGluRS; KIAA1970; MSE1; mtGlnRS; COXPD12
Tractability: PROTAC: ubiquitination databases record sites on it; its protein half-life has been measured.
Gene: Protein-coding gene on chromosome 16 (23,520,754 to 23,557,731, reverse strand). Ensembl gene ENSG00000103356.
Subcellular location: Mitochondrion matrix
Subcellular location (Human Protein Atlas): Mitochondria; Nucleoplasm
Pathways (Reactome):
Metabolism of proteins: Mitochondrial tRNA aminoacylation
Gene Ontology:
Molecular function: glutamate-tRNA ligase activity; glutamate-tRNA(Gln) ligase activity; aminoacyl-tRNA ligase activity; ATP binding; nucleotide binding; tRNA binding; zinc ion binding
Biological process: glutamyl-tRNA aminoacylation; tRNA aminoacylation for mitochondrial protein translation; tRNA aminoacylation; tRNA aminoacylation for protein translation
Cellular component: mitochondrial matrix; mitochondrion
Genetic constraint (gnomAD): Loss-of-function variants: 44 observed, 49.73 expected, observed/expected ratio (o/e) 0.88, 90% interval 0.69 to 1.14. The upper end of that interval is the gene's LOEUF score, 1.14, which puts it in group 4 of 6, group 1 being the genes least tolerant of losing a copy. Missense variants: 652 observed, 657.69 expected, observed/expected ratio (o/e) 0.99, 90% interval 0.93 to 1.06. Synonymous variants: 297 observed, 278.07 expected, observed/expected ratio (o/e) 1.07, 90% interval 0.97 to 1.18.
Gene-disease validity (ClinGen):
ClinGen rates the evidence that EARS2 causes each of these diseases.
Leigh syndrome (autosomal recessive): Definitive. A progressive neurological disease defined by specific neuropathological features associating brainstem and basal ganglia lesions.
mitochondrial disease (autosomal recessive): Definitive.
Homologues: Orthologues: chimpanzee EARS2 (99% identical), macaque EARS2 (90% identical), dog EARS2 (86% identical), guinea pig EARS2 (86% identical), mouse Ears2 (85% identical), rat Ears2l1 (84% identical), pig EARS2 (80% identical), tropical clawed frog ears2 (62% identical), zebrafish ears2 (57% identical), Drosophila melanogaster GluRS-m (45% identical), Caenorhabditis elegans ears-2 (37% identical). Paralogues in human: EPRS1 (23% identical), QARS1 (18% identical).
Diseases named in the same sentence as EARS2 in open-access papers:
EARS2 is named in the same sentence as 27 diseases in open-access papers, as found by Europe PMC text mining. Sharing a sentence is not in itself a finding about the gene and the disease. The quoted sentences say what the papers report.
Leukoencephalopathy (18 papers, 2013 to 2025). This term describes abnormality of the white matter of the cerebrum resulting from damage to the myelin sheaths of nerve cells. "The hallmark of EARS2 mutations is leukoencephalopathy with thalamus and brainstem involvement and high lactate (LTBL), and similar leukoencephalopathy with high lactate was also observed in patients with AARS2 mutations." (PMID 37975900, 2024). "The patient carrying compound heterozygous EARS2 mutations (c.322C>T, p.R108W; c.334G>C, p.A112P) had childhood-onset ataxia, epilepsy, and leukoencephalopathy with thalamic and brain stem involvement (LTBL)." (PMID 37975900, 2024). "EARS2 mutations are found in individuals having leukoencephalopathy of thalamus and brainstem with high lactate (LTBL)." (PMID 35779338, 2022). "Defects in EARS2 have been associated with a specific clinical syndrome called leukoencephalopathy with thalamus and brainstem involvement and high lactate (LTBL)." (PMID 32887222, 2020). "Pathogenic EARS2 variants have been associated with a rare mitochondrial disorder known as leukoencephalopathy with thalamus and brainstem involvement and high lactate (LTBL)." (PMID 32887222, 2020). "Mutations in DARS2 and EARS2 result in very characteristic MRI phenotypes of leukoencephalopathy with brainstem and spinal cord involvement and lactate elevation (LBSL) and leukoencephalopathy with thalamus and brainstem involvement and high lactate (LTBL)." (PMID 29980628, 2018). "Mutations in the glutamyl-tRNA synthetase (EARS2) cause early onset severe neurological disease (leukoencephalopathy involving the thalamus and brainstem with high lactate, LTBL)." (PMID 24412566, 2014). "It is encoded by the EARS2 gene, thus the missense mutation variants of this gene lead to the impairment of mitochondrial function in the affected tissues, which in turn might develop into mitochondrial disorders, i.e., leukoencephalopathy or leukodystrophy." (PMID 32916978, 2020). "EARS2 mutations were also found in vitro in a patient with leukoencephalopathy, brain calcifications and cysts (LCC; MIM 614924), which is a disease different from COXPD12 in terms of neuroimaging and clinical symptoms." (PMID 32916978, 2020). "A recent report described a disease called leukoencephalopathy with thalamus and brainstem involvement and high lactate (LTBL) linked to mutations encoding mitochondrial glutamyl-tRNA synthetase (EARS2)." (PMID 24917879, 2014). "Pathogenic defects in EARS2 may cause mitochondrial OXPHOS deficiency, which is associated with a rare autosomal-recessive mitochondrial disease, leukoencephalopathy with thalamus and brainstem involvement and high lactate (LTBL)." (PMID 40389993, 2025). "Pathogenic defects in EARS2 may cause mitochondrial OXPHOS deficiency, which is associated with the rare autosomal-recessive mitochondrial disease, leukoencephalopathy with thalamus and brainstem involvement and high lactate (LTBL)." (PMID 40389993, 2025). "For instance, mutations in DARS2 and EARS2 are associated with leukoencephalopathy, not necessarily seen in the clinical presentations of patients with other ARS2 variants." (PMID 30920170, 2019). "A detailed clinical and imaging review of leukoencephalopathy with thalamus and brainstem involvement and high lactate (LTBL) cases reveals both a mild and severe disease phenotype caused by either heterozygous or homozygous EARS2 mutations, which encode mitochondrial glutamyl-tRNA synthetase." (PMID 31839000, 2019).
leukodystrophy (4 papers, 2020 to 2025). Leukodystrophies are a group of rare, progressive, metabolic, genetic diseases that affect the brain, spinal cord and often the peripheral nerves. "For example, leukodystrophy sparing periventricular white matter is linked to EARS2 mutations." (PMID 39405331, 2024). "LysRS are involved in myelin formation and defects in other ARSes (e.g., AARS2, DARS2, EARS2, and LARS2) have been found to be responsible for leukodystrophy." (PMID 33942428, 2021).
epilepsy (3 papers, 2023 to 2025). A brain disorder characterized by episodes of abnormally increased neuronal discharge resulting in transient episodes of sensory or motor neurological dysfunction, or psychic dysfunction. "P5, with compound heterozygous pathogenic variants in the EARS2 gene, was a 1.5-year-old baby girl with early-onset hypoglycemic seizures, inability to hold her head, hypotonia, epilepsy, imaging, and laboratory findings." (PMID 37377599, 2023).
Leigh syndrome (2 papers, 2021 to 2025). "Our WES analysis reveals three heterozygous nuclear variants, MTFMT, NARS2, and EARS2, mapping in genes known to cause COXPD associated with Leigh syndrome." (PMID 35004675, 2021). "Our mitochondrial metabolic and morphometric analyses lend credence to the three heterozygous variants, MTFMT, NARS2, and EARS2, mapping in genes linked to COXPD associated with Leigh syndrome, as a probable cause of the proband’s neurological manifestations and mitochondrial etiology." (PMID 35004675, 2021).
pancreatic cancer (2 papers, 2022 to 2024). "In conclusion, EARS2 expression might be a risk factor for pancreatic cancer in breast cancer patients with PALB2 mutations." (PMID 35779338, 2022). "EARS2 expression might be a risk factor for pancreatic cancer in breast cancer patients with PALB2 mutations." (PMID 35779338, 2022). "There is some evidence of the co-expression of EARS2 with PALB2 in breast and pancreatic cancer and the association of their overexpression with poorer outcomes." (PMID 38052461, 2024). "In renal cancer EARS2 protein expression is a favorable prognostic marker, whereas in pancreatic cancer EARS2 protein expression is an unfavorable prognostic marker." (PMID 35779338, 2022). "By assessing EARS2 expression in breast tumors, the clinician might obtain a second piece of information that, with family history of pancreatic cancer, could inform the decision to perform pancreatic cancer screening." (PMID 35779338, 2022). "Our conclusion that EARS2 expression might be a risk factor for pancreatic cancer in breast cancer patients with PALB2 mutations is based on mRNA expression since there were only 2 pancreatic cancers and no breast cancers with a PALB2 mutation." (PMID 35779338, 2022). "Six genes, EARS2, ARL6IP1, DNAJA3, KNOP1, RPUSD1, and TMEM186, significantly coexpressed with PALB2 in both breast and pancreatic cancer." (PMID 35779338, 2022). "Glutamyl-tRNA synthetase 2 (EARS2) was the only gene coexpressing with PALB2 in the breast and pancreatic cancer subjects that was significantly related to pancreatic cancer survival." (PMID 35779338, 2022). "Glutamyl-tRNA synthetase 2 (EARS2) was the only gene coexpressing with PALB2 in the breast and pancreatic cancer subjects that was significantly related to worse pancreatic cancer survival." (PMID 35779338, 2022). "We evaluated 51 genes in the data sets that gave rise to EARS2 being the ONLY coexpressed gene in both breast and pancreatic cancers." (PMID 35779338, 2022).
breast carcinoma (1 paper, 2022). "PAM50 versus EARS2 gene RNA expression in 67 breast cancer subjects showed highest RNA expression in Luminal B subtype subjects (p = 0.023, one way ANOVA)." (PMID 35779338, 2022).
colorectal cancer (1 paper, 2024). A primary or metastatic malignant neoplasm that affects the colon or rectum. "EARS2 is involved in mitochondrial protein synthesis and was found to be associated with breast, pancreatic, renal, and colorectal cancers." (PMID 38052461, 2024).
COVID-19 (1 paper, 2021). A disease caused by infection with severe acute respiratory syndrome coronavirus 2. "More importantly, this work identifies TARS2, HARS2, and EARS2 as potential key factors involved in COVID-19." (PMID 35153822, 2021). "Although there has been no study to report the tRNA-like elements regulated by TARS2, HARS2 or EARS2, the investigation of the aaRSs-mediated control of viruses or host mRNAs, as well as the function of tRNA-like structures will reveal novel molecular mechanisms for COVID-19." (PMID 35153822, 2021).
respiratory infection (1 paper, 2025). "Herein, we report a novel mutation of EARS2 in a patient with LTBL who experienced recurrent respiratory infection and exhibited disordered B cell function, suggesting a novel EARS2 function in the immune system." (PMID 40389993, 2025).
Respiratory tract infection (1 paper, 2025). An infection of the upper or lower respiratory tract. "Collectively, we report a novel mutation in EARS2 in a patient with LTBL who presented with recurrent respiratory tract infections and a dysregulated immune system, which expands the mutation database." (PMID 40389993, 2025). "The mutation of EARS2 modified protein structure and impaired B-cell function, decreased CD38 expression, and led to dysfunction of mitochondrial metabolism, all of which may account for the recurrent respiratory tract infections and humoral immune disorders observed in LTBL." (PMID 40389993, 2025).
mitochondrial disease (4 papers, 2014 to 2021). "Pathogenic EARS2 variants are associated with the rare mitochondrial disease COXPD 12 (OMIM No. 614924)." (PMID 35004675, 2021).
infection (2 papers, 2021 to 2023). The state of being infected such as from the introduction of a foreign agent such as serum, vaccine, antigenic substance or organism. "PARS2 and EARS2 appear to exert pan-coronavirus antiviral activity as the screen showed sensitization to cell death upon infections with SARS-CoV-2, HKU5-SARSCoV-1-S, and MERS-CoV." (PMID 38108455, 2023). "PARS2 and EARS2 showed significant negative Z scores upon infections with SARS-CoV-2, HKU5-SARS-CoV-1-S, and MERS-CoV (WT and tissue-adapted), suggesting possible roles as pan-coronavirus inhibitors." (PMID 35153822, 2021). "In addition, EARS2 got significant negative Z scores across infections with three CoVs, and it was also revealed as a significant IN gene overlapping three groups upon SARS-CoV-2 infection." (PMID 35153822, 2021). "In addition, EARS2 displayed a significant negative Z score upon infection with rVSV-SARS-CoV-2-S, implying a role in SARS-CoV-2 entry process." (PMID 35153822, 2021).
EARS2 also shares sentences with these, for which no sentence is quoted: Autosomal recessive spastic ataxia with leukoencephalopathy (1 paper); breast tumors (1); cancer (1); Cerebral ischemia (1); duct carcinoma (1); glioblastoma (1); immune disorders (1); Mitochondrial encephalopathy (1); neurodegenerative disease (1); ovarian failure (1); OXPHOS disease (1); renal carcinoma (1); sensorineural hearing loss with (1); spastic ataxia (1); viral infection (1).